TIGIT (T cell immunoreceptor with Ig and ITIM domains)
Diseases named in the same sentence as TIGIT in open-access papers (continued):
Sharing a sentence is not in itself a finding about the gene and the disease.
lymphopenia (3 papers, 2021 to 2024). Reduction in the number of lymphocytes. "Increased expression of TIGIT on CD4 and CD8 cells observed in our IPF cohort may suggest recruitment of T cells from peripheral blood (this explains the peripheral lymphopenia of IPF patients) to the lung interstitium, as described in the histopathological features of IPF." (PMID 38540243, 2024). "Anti-TIGIT mAb administration reverses lymphopenia in CA septic mice but not PH septic mice." (PMID 34100383, 2021).
malaria (3 papers, 2020 to 2023). Malaria is a serious and sometimes fatal disease caused by a parasite that commonly infects a certain type of mosquito which feeds on humans. "TIGIT expression in malaria patients was significantly increased on bulk CD8+ and CD4+ T cell populations." (PMID 32983106, 2020). "In malaria patients we observed an increase of TIGIT on bulk CD8+ and CD4+ T cells." (PMID 32983106, 2020). "In malaria we observed an upregulation of both PD1 and TIGIT on CD8+ and CD4+ T cells compared to healthy donors." (PMID 32983106, 2020). "Thus, malaria-induced CD8+ T cells co-express LAG-3, PD-1, TIGIT, TIM-3, CTLA-4, and CD39 but similarly express more effector molecules compared to those expressing lower levels of co-inhibitory molecules." (PMID 35874786, 2022).
Obesity (3 papers, 2020 to 2023). Accumulation of substantial excess body fat. "Further studies are required to elucidate the role of TIGIT+Tregs in obesity-associated infections." (PMID 37604833, 2023). "It is noteworthy that TIGIT and IDO1 showed stronger co-expression with other immune checkpoints in normal group compared with obesity group." (PMID 33197880, 2020). "In mice, we have found that obesity, induced by 12 weeks of high-fat diet protocol, resulted in a 2-times expansion of the TIGIT+ Treg subset and did not interfere in the TIGIT-Treg compartment in secondary lymphoid organs (unpublished data)." (PMID 37604833, 2023). "Moreover, additional immune checkpoints, such as TIM-3, LAG-3, TIGIT, and EB4, and exhaustion markers, such as TOX, TCF-7, and Eomes, were not increased on CD8 T cells in obesity, suggesting that obesity does not accelerate classical T cell exhaustion." (PMID 35103755, 2022).
oesophageal cancer (3 papers, 2022 to 2025). "Although trials testing the effects of anti TIGIT in oesophageal cancer have begun, there is a paucity of research on the expression patterns of this protein in patients with this disease." (PMID 35804876, 2022). "To conclude, these findings implicate a potential role for PD-1 and TIGIT for maintaining immune tolerance in the oesophagus, suggesting that these ICs may be appropriate ICs to target in oesophageal cancers." (PMID 35245832, 2022). "There is early progress in the development of non-PD-1 checkpoint inhibitors such as anti-LAG3, anti-TIGIT and anti TIM3 therapies in oesophageal cancer, and these are currently being investigated alone or in combination with anti-PD-1." (PMID 35804876, 2022).
pancreatic ductal adenocarcinoma (3 papers, 2022 to 2023). An infiltrating adenocarcinoma that arises from the epithelial cells of the pancreas. "Consistently, we found the expression of TIGIT was also upregulated in T cells after ablation by analyzing the published scRNA-seq data from the pancreatic ductal adenocarcinoma (PDAC) mouse model." (PMID 35320940, 2022).
parasitic infections (3 papers, 2024 to 2025). "Upregulated TIGIT expression on T cells is reportedly associated with impaired immune response in several viral and parasitic infections." (PMID 40526725, 2025). "Recently, several studies have reported that immune checkpoints, including PD-1, CTLA-4, LAG-3, TIM-3, TIGIT, etc., were associated with immune tolerance and immune escape in parasitic infections." (PMID 39456030, 2024). "Elevation in TIGIT expression on T cells, especially on pathogen-exposed activated differentiated effector subsets, has already been observed in various infections, including acute bacterial infection, and mainly chronic viral and parasitical infections." (PMID 40526725, 2025).
schistosomiasis (3 papers, 2023 to 2026). An infectious disease caused by parasitic trematodes of the genus Schistosoma that colonize human blood vessels and release eggs that can cause granulomatous reactions leading to acute (swimmer's itch or acute schistosomiasis syndrome) or chronic disease. "We found that TIGIT, an inhibitory receptor, was significantly highly expressed on NK cells at 4 and 6 weeks post infection, which may be associated with NK cell inhibition in schistosomiasis." (PMID 36930687, 2023).
seminoma (3 papers, 2019 to 2025). A radiosensitive malignant germ cell tumor found in the testis (especially undescended), and extragonadal sites (anterior mediastinum and pineal gland). "Similar results were found in adult seminomas, where high levels of PD-1 and TIGIT were detected on infiltrating T cells, where increased cytotoxic T cell infiltration is associated with favorable outcomes and potential responsiveness to immunotherapy." (PMID 40621458, 2025). "TIGIT showed elevated levels in adult seminoma and EC, similar to its upregulation in pediatric dysgerminomas, suggesting it could be a relevant checkpoint in immune suppression in both age groups for these histologies." (PMID 40621458, 2025).
Sjögren’s syndrome (3 papers, 2023 to 2025). "TIGIT displays a scarce expression within a limited population of Nc-Mono cells, while decreased expression of TIGIT on CD14 + monocytes correlates with clinical features and laboratory parameters of patients with primary Sjögren’s syndrome." (PMID 38742110, 2024).
squamous cell carcinoma (3 papers, 2019 to 2025). A carcinoma arising from squamous epithelial cells. "Aberrant TIGIT expression has been reported in tumor-infiltrating lymphocytes across various cancers, including gastrointestinal, breast, and squamous cell carcinoma." (PMID 41419632, 2025). "Particularly, high densities of TIGIT+ lymphocytes were, for example, seen in squamous cell cancers of various origins." (PMID 30733837, 2019). "Concordantly, we observed higher expression of immune checkpoint proteins (CTLA4, TIGIT, and PDCD1) in the lymphocytes at the invasive front of squamous cell carcinomas." (PMID 41309580, 2025).
testicular germ cell tumor (3 papers, 2022 to 2025). A germ cell tumor arising from the testis. "Additionally, UPF3B expression was positively correlated with most immunoinhibitors, including TGFBR1, IL10RB, CD160, CD274, TIGIT and PDCD1 in UVM, OV, KIHC, and LIHC, but negatively associated with the expression of majority genes in STAD and Testicular Germ Cell Tumors (TGCT)." (PMID 36194583, 2022).
thyroid cancer (3 papers, 2021 to 2023). "Therefore, it can raise possibility that TIGIT expression increases according to aggressiveness of follicular cell-derived thyroid cancer." (PMID 35971106, 2022).
ulcerative colitis (3 papers, 2022 to 2025). An inflammatory bowel disease involving the mucosal surface of the large intestine and rectum. "The balance between memory Th17 cells (mTh17) and memory Treg cells (mTreg) plays a key role in the pathogenesis of ulcerative colitis (UC), and TIGIT signaling is involved in the differentiation of mTh17/mTreg cells." (PMID 38202824, 2024). "In the chronic ulcerative colitis model, during the late inflammatory phase, DSS-treated mice may experience systemic T cell functional exhaustion or increased apoptosis, resulting in a widespread loss of TIGIT expression across subsets and impaired peripheral immune tolerance." (PMID 41465029, 2025).
acute GVHD (2 papers, 2022 to 2023). "A study using a TIGIT-Fc fusion protein, which exerted immunosuppressive effects by binding to CD155 on DCs, demonstrated that TIGIT-Fc delayed the onset of GVHD symptoms and increased survival in model mice with acute GVHD." (PMID 37670328, 2023).
acute lymphoblastic leukemia (2 papers, 2023 to 2025). Leukemia with an acute onset, characterized by the presence of lymphoblasts in the bone marrow and the peripheral blood. "First, in patients with chronic lymphocytic leukemia (CLL), AML, or adult acute lymphoblastic leukemia (ALL), TIGIT is commonly upregulated on CD4+ T cells, CD8+ T cells, Foxp3 + γδ T cells, or NK cells compared with healthy individuals." (PMID 37291608, 2023).
AIDS (2 papers, 2016 to 2022). A syndrome resulting from the acquired deficiency of cellular immunity caused by the human immunodeficiency virus (HIV). "Taken together, rhTIGIT pathway is active in the rhesus macaque model of HIV/AIDS and partially mimics human TIGIT expression and function during HIV infection." (PMID 26741490, 2016). "To explore the role of TIGIT in the rhesus macaque model of HIV/AIDS we cloned rhesus TIGIT (rhTIGIT) (GenBank: KR534505) and observed that it shares 88.11% sequence homology with human TIGIT." (PMID 26741490, 2016). "Given that only clinical trial data for PD-1 and CTLA-4 blockers are available, the data from testing blockers against other ICs (TIGIT, LAG-3, Tim-3, CD160, 2B4, BTLA, and VISTA) may prove highly useful in treatment of AIDs." (PMID 35336991, 2022). "Given the potential to restore anti-HIV-specific CD8+ T cell responses by synergistic modulation of negative checkpoint receptors, we investigated the expression and function of TIGIT in HIV disease pathogenesis, and in the SIV non-human primate model of HIV/AIDS." (PMID 26741490, 2016).
Cirrhosis (2 papers, 2023 to 2024). A chronic disorder of the liver in which liver tissue becomes scarred and is partially replaced by regenerative nodules and fibrotic tissue resulting in loss of liver function. "For example, our previous research found that the level of PD-1+, TIGIT+, TIM-3 co-inhibitory molecules of adaptive immune CD4+, CD8+T, NK cells representing the exhaustion function gradually increased during the pathological process of chronic hepatitis B virus to cirrhosis and progressed HBV-HCC." (PMID 37201112, 2023).
colorectal adenocarcinoma (2 papers, 2019 to 2025). The most common type of colorectal carcinoma. "The TIGIT ligand PVRL2 is highly expressed on tumor cells of patients with colorectal adenocarcinoma, and its interaction with TIGIT strongly correlates with poor clinical outcomes." (PMID 40463500, 2025).
diffuse large B-cell lymphoma (2 papers, 2023 to 2025). "This study aims to investigate the status of natural killer (NK) cells and the role of T-cell immunoreceptor with Ig and ITIM domains (TIGIT)-mediated regulation in diffuse large B-cell lymphoma (DLBCL)." (PMID 40231264, 2025).
endometriosis (2 papers, 2021 to 2022). The growth of functional endometrial tissue in anatomic sites outside the uterine body. "We also identified putative inhibitory interactions between endometriosis immune cells and ectopic FBs rather than eutopic FBs, including KLRB1, TIGIT, and PDCD1, which were highly expressed by NK and T cells, and potentially bind to CLEC2D, NECTIN3, and FAM3C, which were expressed by FBs." (PMID 34233737, 2021).
fungal infection (2 papers, 2022 to 2024). "Our finding that C. albicans interacts with TIGIT has the potential to offer the benefit of using monoclonal antibodies, such as anti-TIGIT antibodies, which could serve as a remedy for cancer and may confer protection against fungal infections." (PMID 39109867, 2024). "Furthermore, we elucidated how TIGIT absence could enhance immunity following fungal infection of TIGIT-KO in comparison to WT mice in vivo." (PMID 39109867, 2024). "Up until now no fungal ligand of TIGIT is known, and the role of TIGIT in fungal infections was hypothesized to only be the cessation of the immune response and the prevention of immunopathology." (PMID 35513379, 2022).
gastric tumors (2 papers, 2019 to 2024). "Furthermore, HEV-high gastric tumors exhibited increased immune-modulating chemokines, activated pathway of type I or II interferon, and upregulated immune checkpoints such as PD-1 and TIGIT." (PMID 39040120, 2024).
Hepatitis (2 papers, 2024 to 2026). Inflammation of the liver. "Among these, randomized controlled trials demonstrated that adding LAG-3 or TIGIT inhibitors to established therapies did not increase the risk of elevated hepatic enzyme levels or hepatitis." (PMID 41660625, 2026).
interstitial lung disease (2 papers, 2021 to 2022). A diverse group of lung diseases that affect the lung parenchyma. "Features of exhaustion, including loss of CD127 and CD28, and expression of TIGIT and PD-1 in CD8 T cells are strongly associated with interstitial lung disease and autoimmune cytopenias, whereas CD8 T cell activation with elevated HLA-DR and CD38 expression predict non-infectious diarrhea." (PMID 35589883, 2022). "An elevated TIGIT+CD226+ CD4 subset with enhanced effector function was observed in patients with DM, especially the patients complicated with interstitial lung disease." (PMID 33413573, 2021).
intrahepatic cholangiocarcinoma (2 papers, 2022 to 2024). A carcinoma that arises from the intrahepatic bile duct epithelium in any site of the intrahepatic biliary tree. "have studied the interaction between malignant cells and regulatory T cells (Tregs) in intrahepatic cholangiocarcinoma (ICC), and found that TIGIT-PVR signal was enriched between Tregs and malignant cells." (PMID 39474422, 2024). "For example, It has been reported that intrahepatic cholangiocarcinoma (CCA) could interact with regulatory T cells (Treg) through the ligand‐receptor (L‐R) pair of TIGIT‐PVR, leading to immunosuppression in intrahepatic CCA (ICC)." (PMID 35124891, 2022).
lupus nephritis (2 papers, 2024 to 2025). Glomerulonephritis in the context of systemic lupus erythematosus. "Exhausted T cells express TIGIT and are not only a feature of tumor immunity but also of SLE and lupus nephritis in the MRL/lpr model of SLE17." (PMID 39828802, 2025). "Exhausted T cells express TIGIT and are not only a feature of tumor immunity but also of SLE and lupus nephritis in the MRL/lpr model of SLE." (PMID 38746373, 2024).
metastatic cancer (2 papers, 2021 to 2023). A carcinoma which has spread from the original site of growth to another anatomic site. "By interacting with TIGIT, NECTIN2 was found to be highly expressed in metastatic non-TNBC cells, and by interacting with TIGIT, metastatic cancer cells were found to inhibit T-cell activation and suppress the immune response." (PMID 34611125, 2021).
pancreatic adenocarcinoma (2 papers, 2022 to 2023). "In pancreatic adenocarcinoma (PDAC), the CD155/TIGIT axis is critical for maintaining immune escape in PDAC, and TIGIT/PD-1 combined with CD40 agonists have good antitumor responses." (PMID 37744276, 2023). "“Profile-B” is made by the 6 molecules differently expressed in Pancreatic adenocarcinoma (PAAD) patients (i.e., TIM3 (HAVCR2), OX40 (TNFRSF4), GITR (TNFRRSF18), TIGIT, LAG3 and CTLA4)." (PMID 36224560, 2022).
Pleural effusion (2 papers, 2020 to 2025). The presence of an excessive amount of fluid in the pleural cavity. "More importantly, compared to the Tregs in the pleural effusion of HP, the Tregs in the MPE of LCP exhibited higher expression levels of CTLA4, TIGIT, and BATF." (PMID 40959273, 2025).
pneumonia (2 papers, 2020 to 2021). An acute, acute and chronic, or chronic inflammation focally or diffusely affecting the lung parenchyma, caused by an infection in one or both of the lungs (by bacteria, viruses, fungi, or mycoplasma.). "This T subset expressed higher levels of T‐cell immunoglobulin and mucin domain‐containing protein 3 (Tim3) and T‐cell immunoreceptor with Ig and ITIM domains (TIGIT) in patients with acute pneumonia and stable pneumonia." (PMID 34841705, 2021). "The expression levels of CD59, CD28, CCR7, CD270, Tim3, Eomes, lymphocyte activation gene‐3 (LAG3), TCRab and TIGIT were higher, while that of OX40, CD45RO, PD‐L1 and CD25 lower in cluster 09 in patients with acute pneumonia." (PMID 34841705, 2021). "The expression levels of CD27, CD28, CD59, OX40, CD40L, CD270, PD‐1, Tim3, EOME, HLA‐DR, TCRab and TIGIT were higher, while CD45, CD45RO and Tbet were lower in cluster 18 of patients with acute pneumonia." (PMID 34841705, 2021).
poorly differentiated thyroid carcinoma (2 papers, 2022 to 2023). "Our IHC results showed that TIGIT expression was detected in cancer cells of MTC and high-grade TC: poorly differentiated thyroid carcinoma (PDTC) and ATC." (PMID 35971106, 2022).
renal carcinoma (2 papers, 2023 to 2025). A carcinoma arising from the epithelium of the renal parenchyma or the renal pelvis. "Taken together, these findings indicated that TIGIT enhanced carcinogenesis of renal carcinoma cells in vitro." (PMID 37035135, 2023). "In renal cancers, the main contributors to PC-1, the axis separating healthy and sick – were the CD86, TIGIT, ICOS, and BTLA genes." (PMID 40788962, 2025). "We explored the expression of TIGIT in renal carcinoma cells (786-O) and normal cells (HK2) and found that the level of TIGIT in tumor cells was significantly increased compared to normal cells." (PMID 37035135, 2023).
serous ovarian cancer (2 papers, 2020 to 2024). "Efforts towards this have identified regulation of CD155, a checkpoint ligand for TIGIT, by FAK, and FAK expression is positively associated with TIGIT checkpoint ligands in human high grade serous ovarian cancer." (PMID 39641590, 2024).
skin cancer (2 papers, 2021 to 2024). "Moreover, other treatment strategies against MCC and other skin cancers are currently under investigation, including PI3K/mTOR inhibitors, domatinostat, adoptive cell therapy, and next-generation immune checkpoint inhibitors, such as anti-TIM-3, anti-TIGIT, and anti-LAD-3." (PMID 38793784, 2024).
thyroid (2 papers, 2019 to 2023). "The immune checkpoint PD-1/PD-L1 axis (CTLA-4, TIGIT, TIM3) activation played an important part in thyroid carcinogenesis." (PMID 37798795, 2023).